TNF (tumor necrosis factor)
Diseases named in the same sentence as TNF in open-access papers (continued):
Sharing a sentence is not in itself a finding about the gene and the disease.
infection (continued). "In severe infection, increased release of thrombopoietin and various inflammatory cytokines, such as interleukin-1, −3 and −6 and tumor necrosis factor-α, result in increased thrombopoiesis and enhanced expression of younger large platelets into the blood circulation." (PMID 29084523, 2017). "Because XPro1595 did not block acute seizures, we used genetically modified animals to further test the hypothesis that TNFα signaling contributes to hyperexcitability after infection." (PMID 28497109, 2017). "Why TNF-α neutralization with anti-TNF vaccination preserved the immune response against infection remains speculative." (PMID 29184553, 2017). "TNF-α is a mononuclear-phagocyte-origin cytokine that has pleiotropic effects on innate host responses to microbes and it recruits inflammatory cells into the site of infection and is overexpressed in AECOPD." (PMID 28352642, 2017). "Subsequently, infection leads to the activation of the nuclear factor-κB (NF-κB) signaling pathway and the production of pro-inflammatory cytokines, such as IL-6 and tumor necrosis factor (TNF), using innate immune cells." (PMID 28935867, 2017). "Previous studies have demonstrated the production of interferon-gamma (IFN-γ), interleukin 12 (IL-12), nitric oxide (NO) and tumour necrosis factor alpha (TNF-α) in early stages of infection and later interleukin 13 (IL-13), interleukin 4 (IL-4) and interleukin 10 (IL-10)." (PMID 28655350, 2017). "Interestingly, IFNβ, CXCL2 and TNF expression control by the M protein is observed in the late stages of the infection in vivo, further corroborating the modulation by MTha of the immune response observed in cellulo." (PMID 29084252, 2017). "MCMV‐M45mutRHIM infection predisposes NIH3T3 cells to TNF‐induced cell death independent of ZBP1 expression (Fig EV4E)." (PMID 28716805, 2017). "However, a relapse of the infection was seen in anti-TNFα-treated animals after cessation of treatment." (PMID 28087648, 2017). "In addition to TNF, Ccr2-/- mice also had a significant defect in IL-12p70 and IL-12p40 production at both 24 and 48 hours post-infection, in agreement with recent findings." (PMID 28384349, 2017). "TNF alpha has been shown to be lipolytic in adipocytes and is relevant to the modulation of lipid body numbers in neutrophils and macrophages under conditions of infection." (PMID 29430572, 2017). "IFN-γ and TNF-α may help to recruit cells to the site of infection and promote the antimicrobial activity of macrophages." (PMID 28122644, 2017). "In this context, it was shown that the trypanosome suppression-inducing factor (TSIF) released by T. brucei during the course of infection induces TNF and NO secretion by classically activated macrophages (i.e., M1), which is a prerequisite for parasite control." (PMID 28596768, 2017). "Furthermore, infection induced a significant increase of IL-6 and TNF-α cytokine serum levels in DM mice." (PMID 29091912, 2017). "First, p62 and many other chaperones are stress-responsive, possibly to ensure different substrates are properly degraded under certain conditions; similarly, ANGPTL8 is a stress-responsive molecule with enhanced expression under TNFα, IL-1β, LPS, or infection." (PMID 29255244, 2017). "Expression of iNOS and pro-inflammatory cytokines (IL-6 and TNF-α) was induced following infection of cells with M. tuberculosis H37Rv, which was significantly (p < 0.05) suppressed by TQ (5 and 10 μg/mL) treatment at the indicated time points, as determined by qRT-PCR." (PMID 28545436, 2017). "Moreover, IL-6 and TNF-α levels significantly increased over course of time in both, ethanol-treated mice and respective controls, indicating ongoing infection and progression of disease." (PMID 29348965, 2017).
infection (continued). "We also measured cytokine production after C. albicans restimulation of splenocytes obtained from 2-DG or BPTES-treated mice after the infection, finding a significant reduction in the production capacity of IL-1β, IL-6, IL-10, TNFα and IFNγ in mice treated with 2-DG." (PMID 28922415, 2017). "However, there was a marked increase in the amount of Il10 mRNA 5 days after infection in both caecum and colon, whereas mRNA levels of the pro-inflammatory cytokines IL-6 and TNFα were unchanged or moderately increased, respectively." (PMID 29241040, 2017). "When stimulated ex vivo with 1μM cognate TagV antigen, TCR-V cells primed by MuPyV.TagV(QN) infection yielded memory cells that were capable of co-producing IFNγ and TNFα to a significantly higher level than those recruited by MuPyV.TagV or MuPyV.TagV(AN) infection." (PMID 28410427, 2017). "Furthermore, the ability of rIFNγ to fuel astrocyte infection was prevented (p < 0.01) by the addition of the anti-TNF antibody infliximab prior to rIFNγ treatment." (PMID 28877735, 2017). "In this work, NZ2114 clearly reduced the levels of TNF-α, and IL-6 compared to the infection group." (PMID 28220445, 2017). "Follow-up from 3 to 5 years indicate a possible safer profile of ustekinumab compared with the TNF-α inhibitors with no increased risk of serious infections and malignancies compared with placebo." (PMID 29104241, 2017). "TNF-α mRNA expression levels were significantly increased at 24 h and 48 h post-infection (P < 0.05), and IL-8 significantly increased at 24 h post-infection (P < 0.05)." (PMID 28484272, 2017). "TNF addition prior to infection also increased the frequency of infected astrocytes when the initial MOI was 1:1 (p < 0.01), but had no impact when the MOI was 10:1 (p = 0.339), when a high frequency (75–80%) of infected cells was already observed in untreated astrocytes." (PMID 28877735, 2017). "Furthermore, high MV levels also correlated with high serum TNF, and levels of MVs and TNF both returned to normal ranges after resolution of infection." (PMID 28599650, 2017). "Low levels of TNF present at the site of infection might be sufficient to control mycobacteria infection." (PMID 29184553, 2017). "All R. typhi-infected CB17 SCID control mice continuously lost weight, developed a high clinical score and succumbed to the infection within 21 days whether treated with isotype antibody or anti-TNFα." (PMID 28222146, 2017). "Additionally, we demonstrated that MCP-1 was rapidly secreted and TNF-α exhibited a more gradual increase throughout the infection of MH-S cells." (PMID 28856457, 2017). "Detection of IL-1β and TNF-α levels in serum samples of mice 48 h post-infection." (PMID 28129375, 2017). "During P. marneffei infection, we found that CYA stimulation could enhance M1-related iNOS mRNA/NO, TNF-α, and IL-12 expression, especially in the second week post-infection." (PMID 28821221, 2017). "In the liver, high amount of TNFα was triggered by the WT CLIB at day 2 after infection." (PMID 28713338, 2017). "In the murine tissue cage infection model, we show that the unmodified or short-chain (acetyl) modified N terminus of S. carnosus Lpp induced neutrophil cell death and tremendous amounts of TNF." (PMID 29269769, 2017). "In the course of infection TNF-α-secretion of CBMO was reduced to 40% as compared to PBMO (p<0.05)." (PMID 28793310, 2017). "We examined the risk of infection associated with starting a TNF inhibitor (TNFi) versus any of the other non-TNFi bDMARDs." (PMID 28610614, 2017). "Calculating the transcript expression of tnf-α as response to S. aureus Newman relative to spontaneous transcript expression, respectively, no increased transcript level was detectable, confirming that the TNF-α release as response to infection is possibly based on prestored TNF-α." (PMID 28553287, 2017).
infection (continued). "Interestingly we found that the levels of TNF-α, IL-2 and IL-4 returned to baseline or were decreased compared to the uninfected control group by 4 to 6 days post-infection." (PMID 28114957, 2017). "The serum levels of TNF-α directly correlated with the infection dose of SL7207." (PMID 28445131, 2017). "Indeed, increased leukocyte recruitment to the brain of IFN-α/βR −/− mice was detected after 6 days of infection and was associated with elevated levels of inflammatory mediators, such as the chemokines CCL5 and CXCL1 and the cytokines IL-1β and TNF-α." (PMID 28442607, 2017). "Specifically, when cells were pre-treated with Leishmania-derived exosomes followed by infection with Leishmania parasites, there was a reduction in release of pro-inflammatory cytokines IL-8, IL-12 and TNF, and an increase in the anti-inflammatory cytokine IL-10, compared to the untreated cells." (PMID 28599650, 2017). "The data showed that levels of IL-12 and TNF-α were significantly higher in the conditioned media from alveolar macrophages two weeks post-infection than both the control group and the fourth week post-infection group." (PMID 28821221, 2017). "We then confirmed that knockdown of the CD147 expression by miR-US25-1-5p could specifically reduce the activation of IFNB1 and interferon-related gene ISG15 and the NF-κB downstream genes IL-6 and TNF-α induced by HCMV early infection." (PMID 29194430, 2017). "There was a lower infection rate and lower antigen load in mice treated with anti-TNF-α antibody." (PMID 28246365, 2017). "Therefore, we tested if SseK effectors inhibit TNF-α-induced cell death during infection of macrophages." (PMID 28069818, 2017). "In similar lines, internalization of TNFR1 in infected macrophages could have contributed for infection mediated blocking of NO in TNF-primed macrophages." (PMID 29375545, 2017). "As determined by ELISA analyses, HSV-2 WT infection strongly enhanced the production of TNF-α, IL-6, IL-8 and CCL2, but the levels of these proinflammatory cytokines and chemokines were inhibited in End1/E6E7 cells which were infected with the Us2 mutant of HSV-2." (PMID 28827540, 2017). "During CMV lytic infection, pro‐inflammatory cytokines IL‐6 and TNF‐α increased remarkably and anti‐inflammatory cytokine IL‐5 decreased, which may exacerbate UC." (PMID 29226079, 2017). "As one of the most crucial proinflammatory cytokines, IL-17A plays an important role in host defense against pathogen infection by stimulating cytokines (TNF-α, GM-CSF, etc) and chemokines (CXCL1, CXCL2, IL-8, etc) expression leading to neutrophil expansion and chemotaxis." (PMID 28035060, 2017). "During lytic infection, increased pro‐inflammatory cytokines IL‐6 and TNF‐α and decreased anti‐inflammatory cytokine IL‐5 may exacerbate UC." (PMID 29226079, 2017). "Therefore, we investigated the effects of UL48 and UL45 on TNFα-induced NF-κB activation in the late stages of infection." (PMID 28570668, 2017). "HCMV also partially blocks TNF-α signaling through downregulation of TNFR1 surface expression during lytic infection, while IL-1β- and TNF-α-induced expression of the chemokine monocyte chemoattractant protein 1 (MCP-1) is blocked at the level of transcription." (PMID 28270578, 2017). "The expression levels of IFN-γ and TNF-α in the culture supernatant of the splenocytes stimulated with BMSA increased more compared with those in the sera of BMSA vaccinated animal groups during all stages of infection." (PMID 29312230, 2017). "From these analyses we conclude that H. diminuta and T. muris antigens can trigger an early pro-inflammatory response with increased TNF-α both in the absence and presence of Mtb-infection which is then shifted towards an anti-inflammatory response with a synergistic increase of IL-10." (PMID 28192437, 2017). "Moreover, M(LPS + IFN-γ) cells had reduced production of TNF-α after infection but were still producing significantly higher amounts than M0 and M(IL-4)." (PMID 29250063, 2017).
infection (continued). "The results showed that the expressions of TNF-α, IL-12, IL-5, IL-10 and GM-CSF in serum increased from five weeks post-infection and to peak levels at week 6 post-infection; however, as typical type 1 cytokines, the levels of IL-2 and IFN-γ in serum did not change during the key period." (PMID 28539607, 2017). "Low serum concentrations of GM-CSF and TNF-α correlated with pocket infection." (PMID 28264059, 2017). "The production of IL-1β and TNF, as well as the expression of inducible nitric oxidase synthase (iNOS), were also downregulated post-infection in vivo." (PMID 28824166, 2017). "Several studies showed that PRRSV down-regulated TNF-α production in the early stage of infection, which may be used by virus to circumvent infected cell apoptosis." (PMID 28839507, 2017). "However, upon cessation of antibiotic treatment a relapse of the infection was seen only in the anti-TNFα-treated mice." (PMID 28087648, 2017). "IL-1β, IL-6, and TNF-α are proinflammatory cytokines released by activated macrophages, are involved in the upregulation of inflammatory reactions, and are important contributors to the inflammatory response to infection." (PMID 28255203, 2017). "Additionally, Trim29-KO mice had higher concentrations of IFN-I, IL-6, and TNF-α in the serum than did their WT littermates after infection with HSV-1." (PMID 29038422, 2017). "Masp2−/− mice had significantly lower brain levels of interleukin (IL)-1β (median 3.46 vs. 5.33 ng/mg tissue, P = 0.045), IL-10 (1.04 vs. 1.70 ng/mg tissue, P = 0.038), and TNF-α (9.32 vs. 22.58 ng/mg tissue, P = 0.025) compared to WT mice at 30 h after infection." (PMID 28086930, 2017). "Further enhancement of neutrophil accumulation could be mediated by chemotactic factors stimulated by inflammatory cytokines IL-1β and TNFα, which we found increased with infection." (PMID 28591228, 2017). "However, it has long been established that infection with M. tuberculosis sensitises fibroblasts to TNFα toxicity." (PMID 28892415, 2017). "Thus, reactivation of an infection due to anti-inflammatory/immunosuppressive anti-TNFα antibodies can be effectively treated with prompt administration of antibiotics." (PMID 28087648, 2017). "Furthermore, TNF-α neutralization was able to effectively reduce infection-induced exacerbation of HDM-allergic reactions despite minor or no reduction of pulmonary Th1, Th17, and Th2 cells, respectively." (PMID 29184554, 2017). "Indeed, hyphae and muriform cells infection induced high levels of TNF-α, IL-1β and IL-6 during the disease establishment stage." (PMID 28355277, 2017). "TNF-α is a primary signaling molecule in systemic inflammatory reactions and is a vital component of the acute phase response; IFNγ is a key signaling molecule in clearance of intracellular pathogen infections." (PMID 29375568, 2017). "When patients were stratified by infection status, we observed increases in TNF-α, CRP, TGF-β, IL-4, IL-6, IL-10, IL-17, and IL-23, and a decrease in IFN-γ in both uninfected and infected patients when compared with control subjects at most of the three time points." (PMID 27682880, 2017). "IL-6 and TNF alpha are involved with the infection inflammation and their levels will be increased." (PMID 28335413, 2017). "Modulation of TNF expression through lncRNAs is a new reported mechanism which might possibly be employed by other pathogens interfering with TNF levels to establish infection." (PMID 28401065, 2017). "ΔN146-infected cells, similar to the LPS-treated cells, expressed and secreted copious levels of type I interferon β (IFN-β), IL-1β, IL-6 and tumor necrosis factor α (TNF-α) 12 h post infection whereas these cytokines were barely detectable in supernatants from mock infected cells." (PMID 28150813, 2017). "Furthermore, CC16 modulates lung inflammatory responses to infection, injury, and allergen challenge by downregulating pro-inflammatory cytokines including IFNγ, IL-1, IL-6 and TNFα." (PMID 28380043, 2017).
infection (continued). "Anti-TNF therapy should be withhold while the infection is treated." (PMID 28146077, 2017). "Expression of the pro-inflammatory cytokines IL-6 and TNF-α was induced following infection of cells with M. tuberculosis H37Rv, which was significantly (p < 0.05) suppressed by TQ (5 and 10 μg/mL) treatment at the indicated time points, as determined by qRT-PCR." (PMID 28545436, 2017). "It is a pharmacological reference for anti-TNF-α blockade in animal models of infection." (PMID 29184553, 2017). "This could serve as an alternate/additional mechanism by which TRM are able to participate in the protective response to infection via production of TNF-α and recruitment of innate and/or antigen-presenting cells." (PMID 28424687, 2017). "TNF-α is involved in both parasite control and infection mediated pathology." (PMID 28655350, 2017). "TNF is another cytokine that is secreted by macrophages early in infection." (PMID 28845089, 2017). "TNFα release tendentially correlated inversely with infection rate (r = −0.63)." (PMID 29312350, 2017). "We thus wondered whether neutralization of TNF-α also attenuates infection-induced exacerbation of AAI." (PMID 29184554, 2017). "TNF-α is a pleiotropic cytokine expressed by many cell types in response to infection or injury." (PMID 28629363, 2017). "All infected mice could secrete IL-6 and TNF-α at 1 day post infection, while the uninfected mice secrete minimal level of IL-6 and TNF-α." (PMID 28468643, 2017). "TNF-α is a proinflammatory cytokine which can act on endothelial cells to stimulate expression of adhesion molecules facilitating the extravasation of neutrophils into the site of infection on the mucosal tissue." (PMID 29391865, 2017). "Furthermore, the infection of primary cultured microglia with P. gingivalis also significantly increased the secretion of IL-6 and TNF-α, and the accumulation of NO metabolites." (PMID 28924232, 2017). "Hence, large intestinal IL-6 secretion as well as TNF and IL-18 mRNA levels were higher in NOD2−/− as compared to WT mice upon pathogenic infection, whereas C. jejuni induced colonic IL-22 down-regulation occurred in WT mice only." (PMID 28127403, 2017). "High level of TNF-α was observed post REV-SNV infection, which may result in severe damage of immune organs and immune dysfunction." (PMID 29312337, 2017). "Notably, NSC61610 treatment reduced expression of TNFα, at day 7 post-infection, and MCP1 at days 3 and 7 post-infection." (PMID 28270815, 2017). "GPT levels in CD4+IFNγ-/- T cell recipients including those that succumbed to the infection were generally normal, whether treated with isotype antibody or anti-TNFα, while serum GPT was enhanced in control animals compared to non-infected mice." (PMID 28222146, 2017). "Due to infection, IL-6 and TNF-α significantly increased at 24 hours." (PMID 29348965, 2017). "When serious infections occur, withdrawal of anti-TNF therapy may be necessary until the infection has been identified and properly treated." (PMID 28358311, 2017). "Infection with SFV inhibited proliferation of BHK-21 and LLC cells in vitro independent on whether SFV-encoded TNF-α or IFN-γ." (PMID 29276511, 2017). "The effects of RvD1 and HO-1 on TNF-α production may differ according to the infection model or parasite species, and additional studies with other Leishmania species are necessary to confirm this hypothesis." (PMID 28393908, 2017). "In our study, we also show that CXCR3 regulates CD8 and CD8+TNF-a+ cell migration after infection." (PMID 29552679, 2017). "While augmentation of TNF signalling by IL1β has been described in macrophages before, we believe that this is the first time that IL1β activation was shown to be enhanced by TNF in Mtb-infection." (PMID 28863187, 2017).